LOXL4 (lysyl oxidase like 4)
Description:
Catalyzes the oxidative deamination of lysine and hydroxylysine residues in collagen and elastin, resulting in the formation of covalent cross-linkages, and the stabilization of collagen and elastin fibers.
Synonyms: LOXC; FLJ21889
Tractability: Small molecule: a high-quality ligand is known. Antibody: UniProt places it where antibodies can reach, with high confidence; UniProt predicts a signal peptide or a membrane-spanning region; its Gene Ontology location is reachable by antibodies, with medium confidence. PROTAC: a small molecule that binds it is known.
Target class: Enzyme; Oxidoreductase
Gene: Protein-coding gene on chromosome 10 (98,247,690 to 98,268,650, reverse strand). Ensembl gene ENSG00000138131.
Subcellular location: Secreted, extracellular space
Subcellular location (Human Protein Atlas): Vesicles; Predicted to be secreted
Pathways (Reactome):
Extracellular matrix organization: Crosslinking of collagen fibrils; Elastic fibre formation
Gene Ontology:
Molecular function: protein binding; protein-lysine 6-oxidase activity; copper ion binding; oxidoreductase activity, acting on the CH-NH2 group of donors, oxygen as acceptor
Biological process: collagen fibril organization
Cellular component: extracellular exosome; receptor complex; elastic fiber; extracellular matrix; extracellular region; membrane
Genetic constraint (gnomAD): Loss-of-function variants: 69 observed, 89.32 expected, observed/expected ratio (o/e) 0.77, 90% interval 0.63 to 0.94. The upper end of that interval is the gene's LOEUF score, 0.94, which puts it in group 4 of 6, group 1 being the genes least tolerant of losing a copy. Missense variants: 979 observed, 1,048.7 expected, observed/expected ratio (o/e) 0.93, 90% interval 0.88 to 0.98. Synonymous variants: 352 observed, 408.34 expected, observed/expected ratio (o/e) 0.86, 90% interval 0.79 to 0.94.
Homologues: Orthologues: chimpanzee LOXL4 (99% identical), macaque LOXL4 (98% identical), rabbit LOXL4 (89% identical), dog LOXL4 (88% identical), mouse Loxl4 (87% identical), pig LOXL4 (87% identical), rat Loxl4 (86% identical), guinea pig LOXL4 (85% identical), tropical clawed frog loxl4 (63% identical), zebrafish loxl4 (57% identical), zebrafish LOXL4 (28% identical). Paralogues in human: LOXL3 (55% identical), LOXL2 (54% identical), DMBT1 (27% identical), CD163 (25% identical), SSC5D (24% identical), CD163L1 (24% identical), PRSS12 (21% identical), SCART1 (21% identical), LOXL1 (21% identical), LOX (18% identical), SSC4D (14% identical), CD6 (13% identical), and 3 more.
Diseases named in the same sentence as LOXL4 in open-access papers:
LOXL4 is named in the same sentence as 59 diseases in open-access papers, as found by Europe PMC text mining. Sharing a sentence is not in itself a finding about the gene and the disease. The quoted sentences say what the papers report.
breast carcinoma (21 papers, 2012 to 2024). "EZH2 is positively correlated with LOXL4 expression and tumor-associated macrophage infiltration (TAM), and LOXL4 knockdown can inhibit the proliferation and metastasis of breast cancer cells." (PMID 36293126, 2022). "The BreastMark website was used to explore the association between LOXL4 and collagen I and IV expression and OS in breast cancer patients." (PMID 28060764, 2017). "Although extensive preclinical research has advanced our understanding of the mechanisms by which the LOX family increases fibrosis in the ECM, few studies have linked LOXL4 expression with clinical outcomes in breast cancer patients." (PMID 28060764, 2017). "Expression of LOXL4 can be activated by hypoxia and is positively associated with the invasive/metastatic state of breast cancer cells." (PMID 25311867, 2014). "Given that EZH2-miR-29b/miR-30d-LOXL4 signaling pathway was associated with tumor progression, we next asked whether the expression of these genes was associated with poor prognosis in breast cancer patients." (PMID 32754259, 2020). "Indeed, a correlation between high EZH2 expression and shorter overall survival was observed in patients with estrogen receptor (ER)-positive breast cancers, while low expression of LOXL4 and high level of miR-30d was associated with good prognosis." (PMID 32754259, 2020). "Combined assessment of EZH2, LOXL4, miR-29/miR-30d and macrophage infiltration may be a more effective diagnostic method for breast cancer." (PMID 32754259, 2020). "In contrast, another study showed that LOXL4 downregulation promotes primary tumor growth and lung metastasis in mouse models of breast cancer, and that low LOXL4 expression is associated with poor overall survival of breast cancer patients." (PMID 31130685, 2019). "Furthermore, we found that low LOXL4 expression was associated with poorer overall survival in breast cancer patients." (PMID 28060764, 2017). "In addition, weak LOXL4 expression was associated with poor overall survival in breast cancer patients from the BreastMark dataset, and this association was strongest in triple-negative breast cancer patients." (PMID 28060764, 2017). "In the current study, we demonstrated that blocking EZH2 activity by EZH2 inhibitors or EZH2 siRNAs significantly reduced the expression of LOXL4 associated with low H3K27me3 expression, suggesting that coordinated epigenetic silencing may exist in breast cancer cells." (PMID 32754259, 2020). "Interestingly, LOXL4 displays a very different mRNA expression profile, which may be associated with a different, yet unknown biological role in breast cancer." (PMID 26265048, 2015). "According to the analysis of the Cancer Genome Atlas (TCGA) database, LOXL1 is expressed at elevated levels in breast cancer (p< 0.05), whereas LOXL4 is expressed at low levels (p < 0.05)." (PMID 39247609, 2024). "Although the tumour-suppressive function of LOXL4 has been documented in bladder cancer, hepatocellular carcinoma, prostate cancer, and breast cancer, its role in other types of tumours remains ambiguous and warrants further exploration." (PMID 39247609, 2024). "Considering the past and present findings together, we suggest that our developed S100A8/A9-mAb (Ab45) combined with the LOXL4-mAb will be more effective than any single inhibitor for the prevention of breast cancer outgrowth." (PMID 37091157, 2023). "LOXL4 has a new role in breast cancer progression that occurs via an interaction with annexin A2 and integrin β-1 on the cell surface." (PMID 37091157, 2023). "Extracellular matrix remodeling in the cancer milieu by LOX family members is a well-known function of LOX proteins, and we, therefore, sought to identify the still-unidentified role of upregulated LOXL4 in breast cancer." (PMID 37091157, 2023). "We revealed that LOXL4 is highly upregulated in breast cancer cells, and we thus sought to define an unidentified role of LOXL4 in breast cancer." (PMID 37091157, 2023).
breast carcinoma (continued). "It should be noted that the function of LOXL4 in the progression of breast cancer is a contentious topic." (PMID 37091157, 2023). "It was also reported that the enhancer of zeste homolog 2(EZH2) in breast cancer cells represses the transcription of miR-29b and miR-30d by catalyzing H3K27me3, thereby promoting the expression of LOXL4." (PMID 36293126, 2022). "Accumulating evidence suggest LOXL4 an oncoprotein in several tumors, such as hepatocellular carcinoma, lung cancer and breast cancer." (PMID 35433829, 2022). "MiR-29 is another cancer protecting geromiR and its downregulation promotes metastasis and immune microenvironment remodeling in breast cancer via the regulation of LOXL4." (PMID 34062897, 2021). "Our study identified an important transcriptional axis comprised of EZH2, miR-29b/miR-30d, and LOXL4, which participated in driving the development of breast cancer by regulating macrophage activation." (PMID 32754259, 2020). "We further demonstrated that EZH2-mediated epigenetic silencing of miR-29b or miR-30d reprogrammed the expression of LOXL4, which influenced cell proliferation and metastasis in the progression of breast cancer." (PMID 32754259, 2020). "Our study showed that the EZH2-miR-29b/miR-30d-LOXL4 axis was involved in the progression of breast cancer cells." (PMID 32754259, 2020). "Immunohistochemical analysis of human breast cancer specimens and flow cytometry analysis of tumor-infiltrating macrophages in mice showed a positive association of EZH2 with LOXL4 expression and macrophage infiltration." (PMID 32754259, 2020). "Various cellular analyses showed that the proliferation and migration of breast cancer cells were significantly impaired by LOXL4 knock-down." (PMID 32754259, 2020). "We investigated the roles of EZH2 and LOXL4 in breast cancer by treating MDA-MB-231 cells with numerous EZH2 inhibitors, such as DZNep, GSK343, UNC1999, or EPZ005687." (PMID 32754259, 2020). "The understanding of molecular mechanisms underlying the EZH2-miR-29b/miR-30d-LOXL4 axis affords a novel insight in diagnosis, prognosis, and molecularly targeted therapy of breast cancer and may provide a novel therapeutic approach for breast cancer treatment in the clinic." (PMID 32754259, 2020). "Together, these data strongly suggested that LOXL4 had a pivotal role in the promotion of breast cancer tumorigenesis and metastasis in vitro and in vivo." (PMID 32754259, 2020). "Our study has illustrated that EZH2-miR-29b/miR-30d-LOXL4 signaling pathway is critical for the proliferation and metastasis of breast cancer cells." (PMID 32754259, 2020). "Overexpression of miR-29b and miR-30d inhibited LOXL4 expression, resulting in impaired proliferation, migration, tumorigenesis, and metastasis of breast cancer cells." (PMID 32754259, 2020). "We evaluated the correlation between EZH2 and miR-29b/30d in breast cancer cells and found an inverse correlation between miR-29b/30d and LOXL4 mRNA by starBase v2.0 analysis." (PMID 32754259, 2020). "A positive correlation between EZH2 and LOXL4 expression was also detected in breast cancer patient samples." (PMID 32754259, 2020). "In breast cancer, LOXL4, LOX, and LOXL2, which are expressed in a hypoxia-inducible factor 1-dependent manner, recruit bone marrow-derived cells and facilitate colonization of the lungs." (PMID 28060764, 2017). "Similarly, based on an OS analysis using data from the public database at the BreastMark website, we found that low LOXL4 expression was also associated with poor OS in breast cancer patients, suggesting that LOXL4 expression could be a useful prognostic marker in breast cancer." (PMID 28060764, 2017). "We also found that LOXL4 expression differed among the hBCCs based on the breast cancer subtype to which they belonged." (PMID 28060764, 2017).
breast carcinoma (continued). "To determine the effects of lysyl oxidase-like 4 (LOXL4) expression on breast tumor formation and metastasis, we evaluated primary tumor growth and lung metastasis in mice injected with LOXL4-knockdown MDA-MB-231 triple-negative human breast cancer cells." (PMID 28060764, 2017). "Additional studies are needed to investigate the different roles of LOXL4 in breast cancer subtypes, particularly in TNBC." (PMID 28060764, 2017). "LOXL4 was found to have higher average mRNA transcript levels in healthy tissue compared with breast cancer samples." (PMID 26265048, 2015). "Developing small molecule inhibitors targeting LOXL4 could provide promising therapeutic options for breast cancer." (PMID 39247609, 2024). "This underscores the crucial role of LOXL4 in driving the onset and progression of breast cancer." (PMID 39247609, 2024). "Collectively, these data suggested that EZH2 was a critical regulator of LOXL4 in breast cancer." (PMID 32754259, 2020). "We explored the regulatory mechanism of EZH2, miR-29b/miR-30d, and LOXL4 in breast cancer cells by qRT-PCR, Western blotting, cell proliferation, colony formation, and wound healing assays, xenograft experiments, dual-luciferase reporter assay, and chromatin immunoprecipitation." (PMID 32754259, 2020). "Furthermore, we examined the role of LOXL4 in breast cancer metastasis in vivo by intravenous injection of the luciferase-labeled MDA-MB-231-control or -shLOXL4 cells into nude mice." (PMID 32754259, 2020). "The results showed that macrophage infiltration was positively correlated with EZH2 and LOXL4 expression, implying that tumor-associated macrophages (TAM) may play a vital role in EZH2/LOXL4-mediated progression of breast cancer." (PMID 32754259, 2020). "LOXL4 is also known to promote proliferation and metastasis of gastric cancers and breast cancer." (PMID 32727620, 2020). "Thus, our data indicated that the EZH2-miR-29b/miR-30d-LOXL4 signaling axis regulated macrophage activation and collagen remodeling in breast cancer." (PMID 32754259, 2020). "Besides the MMPs, the enzymes such as LOXL2, LOXL4, procollagen lysyl hydroxylase-2, and heparanase also regulate breast cancer progression." (PMID 29983921, 2018). "Although recent studies have examined the role of LOXL4 in breast cancer, the explanation for the seemingly contradictory results obtained in cell lines and in xenograft models remains unclear." (PMID 28060764, 2017). "Interestingly, OS was poorest in breast cancer patients with both low LOXL4 levels and high collagen I or IV expression (P = 0.037, HR = 0.6718 and P = 0.037, HR = 0.6619, respectively)." (PMID 28060764, 2017). "In addition, we evaluated the clinical significance of LOXL4 in human breast cancer patients using a public database with overall survival (OS) information." (PMID 28060764, 2017). "It is therefore likely that the role of LOXL4 may depend on heterogenous traits that vary in different types of breast cancer." (PMID 28060764, 2017). "In addition, we analyzed overall survival in breast cancer patients based on LOXL4 expression using a public online database." (PMID 28060764, 2017). "Although many studies have been conducted to elucidate the role of LOXL4 in cancer, the precise mechanisms by which LOXL4 suppresses tumors or promotes metastasis in breast cancer remain largely unknown." (PMID 28060764, 2017). "In light of this interesting result, we suspected that the secreted LOXL4 may bind with cell-surface annexin A2 and catalyze it, resulting in integrin β-1 enrichment on the cell surface, which could work to promote the progression of breast cancer." (PMID 37091157, 2023). "To date, how EZH2 regulates LOXL4 in the progression of breast cancer remains unclear." (PMID 32754259, 2020). "The results implied that EZH2 might regulate the progression of breast cancer through LOXL4." (PMID 32754259, 2020).
breast carcinoma (continued). "The combination of low LOXL4 expression and high collagen levels has been correlated with decreased hazard ratios (HRs) for both OS and DFS in breast cancer patients, particularly those with the HER2+ subtype." (PMID 39247609, 2024). "LOXL4 was the direct target of miR-29b and miR-30d, and inhibition of EZH2 reduced LOXL4 expression in breast cancer cells." (PMID 32754259, 2020). "Our data provide valuable insights into the EZH2 role as a key epigenetic regulator of the ECM and also highlight the importance of performing preclinical studies in breast cancer that target EZH2 and LOXL4." (PMID 32754259, 2020). "In our study, we observed that LOXL4 expression was positively correlated with EZH2 expression and macrophage infiltration, evidenced by CD68 staining in human breast cancer tissues." (PMID 32754259, 2020). "Cell characterization assays after LOXL4 knockdown were also conducted using MCF-7 (luminal subtype) and BT-549 (TN subtype) breast cancer cells." (PMID 28060764, 2017). "In the present study, we demonstrated that knockdown of LOXL4 expression promoted primary tumor growth and lung metastasis in MDA-MB-231 cell xenograft models of breast cancer." (PMID 28060764, 2017). "Except for LOXL4, all enzymes of the LOX family, as well as HIF-1α, were upregulated in breast cancer samples." (PMID 26265048, 2015). "Both LOXL4 and HIF-1α mRNA levels were significantly higher in this breast cancer patient group than in ER-positive samples." (PMID 26265048, 2015). "The relationship between LOXL4 and S100A8/A9 in breast cancer progression remains to be discussed." (PMID 37091157, 2023). "Currently, the functions of LOXL4 regulated by EZH2 in breast cancer are not understood." (PMID 32754259, 2020). "Further analysis of data derived from the GSE9014 set 35 showed that the expression of LOXL4, but not LOXL3, was significantly higher in breast cancer samples than in normal breast samples." (PMID 32754259, 2020). "We speculate that while the impact of LOXL3 inhibition may vary with breast cancer subtype, the therapeutical inhibition of LOX, LOXL1 and LOXL2 but not of LOXL4 may be the most beneficial." (PMID 35800439, 2022). "Overall, we speculate that while the impact of LOXL3 inhibition may vary with breast cancer subtype, the specific therapeutical inhibition of both LOXL1 and LOXL2 but not of LOXL4 may be beneficial in breast cancer." (PMID 35800439, 2022). "This was in contrast with the expression of known HIF target genes involved in breast cancer metastasis not included in the hypoxia signatures (LOX, LOXL2, LOXL4, CCL2, L1CAM, ANGPT1, and ANGPT2), whose expression showed a positive correlation with the signatures." (PMID 29540773, 2018). "Although we did not investigate the effects of interactions between LOXL4 and NOX on collagen production in this study, NOX might also contribute to the LOXL4 knockdown-induced increase in collagen synthesis in breast cancer cells." (PMID 28060764, 2017).